VAPB (VAMP associated protein B and C)
Description:
Endoplasmic reticulum (ER)-anchored protein that mediates the formation of contact sites between the ER and endosomes via interaction with FFAT motif-containing proteins such as STARD3 or WDR44. Interacts with STARD3 in a FFAT motif phosphorylation dependent manner. Via interaction with WDR44 participates in neosynthesized protein export. Participates in the endoplasmic reticulum unfolded protein response (UPR) by inducing ERN1/IRE1 activity. Involved in cellular calcium homeostasis regulation.
Synonyms: VAP-B; VAP-C; ALS8; VAMP-B
Tractability: Antibody: UniProt predicts a signal peptide or a membrane-spanning region; its Gene Ontology location is reachable by antibodies, with medium confidence. PROTAC: UniProt records ubiquitination sites on it; ubiquitination databases record sites on it; its protein half-life has been measured.
Gene: Protein-coding gene on chromosome 20 (58,389,119 to 58,451,101, forward strand). Ensembl gene ENSG00000124164.
Subcellular location: Endoplasmic reticulum membrane
Subcellular location (Human Protein Atlas): Endoplasmic reticulum
Pathways (Reactome):
Signal Transduction: RAC2 GTPase cycle; RHOA GTPase cycle; RHOC GTPase cycle; RHOD GTPase cycle; RHOG GTPase cycle
Metabolism: Sphingolipid de novo biosynthesis
Gene Ontology:
Molecular function: beta-tubulin binding; cadherin binding; enzyme binding; FFAT motif binding; microtubule binding; protein binding; protein heterodimerization activity; protein homodimerization activity; endoplasmic reticulum-plasma membrane adaptor activity; protein-membrane adaptor activity
Biological process: cholesterol transport; COPII-coated vesicle budding; endoplasmic reticulum organization; endoplasmic reticulum to Golgi vesicle-mediated transport; endoplasmic reticulum unfolded protein response; intracellular calcium ion homeostasis; IRE1-mediated unfolded protein response; positive regulation of viral genome replication; 1-phosphatidyl-1D-myo-inositol 4,5-bisphosphate metabolic process; endoplasmic reticulum membrane organization; host-mediated activation of viral genome replication; host-mediated suppression of viral genome replication; viral release from host cell
Cellular component: cytoplasm; endoplasmic reticulum; endoplasmic reticulum exit site; endoplasmic reticulum membrane; Golgi apparatus; endoplasmic reticulum-plasma membrane contact site; glutamatergic synapse; postsynapse; presynapse
Genetic constraint (gnomAD): Loss-of-function variants: 7 observed, 18.81 expected, observed/expected ratio (o/e) 0.37, 90% interval 0.21 to 0.7. The upper end of that interval is the gene's LOEUF score, 0.7, which puts it in group 2 of 6, group 1 being the genes least tolerant of losing a copy. Missense variants: 232 observed, 263.01 expected, observed/expected ratio (o/e) 0.88, 90% interval 0.79 to 0.98. Synonymous variants: 100 observed, 101.25 expected, observed/expected ratio (o/e) 0.99, 90% interval 0.84 to 1.17.
Gene-disease validity (ClinGen):
ClinGen rates the evidence that VAPB causes each of these diseases.
amyotrophic lateral sclerosis type 8 (autosomal dominant): Definitive.
Homologues: Orthologues: chimpanzee VAPB (100% identical), macaque VAPB (100% identical), dog VAPB (96% identical), pig VAPB (94% identical), mouse Vapb (90% identical), guinea pig VAPB (89% identical), rabbit VAPB (84% identical), rat Vapb (82% identical), tropical clawed frog vapb (79% identical), zebrafish vapb (73% identical), Drosophila melanogaster Vap33 (39% identical), Caenorhabditis elegans F42G2.5 (37% identical), and 6 more. Paralogues in human: VAPA (62% identical).
Diseases named in the same sentence as VAPB in open-access papers:
VAPB is named in the same sentence as 81 diseases in open-access papers, as found by Europe PMC text mining. Sharing a sentence is not in itself a finding about the gene and the disease. The quoted sentences say what the papers report.
amyotrophic lateral sclerosis (81 papers, 2011 to 2025). Amyotrophic lateral sclerosis (ALS) is a neurodegenerative disease characterized by progressive muscular paralysis reflecting degeneration of motor neurons in the primary motor cortex, corticospinal tracts, brainstem and spinal cord. "ALS8 is a rare and distinct subtype of amyotrophic lateral sclerosis, marked by mutations in the VAPB gene and a slower disease progression." (PMID 39897290, 2025). "Amyotrophic lateral sclerosis type 8 (ALS8) is a rare familial subtype of ALS caused by mutations in the vesicle-associated membrane protein-associated protein B (VAPB) gene, particularly the p.P56S mutation." (PMID 39897290, 2025). "VAPB is directly associated with amyotrophic lateral sclerosis (ALS) and regulates calcium homeostasis in ALS." (PMID 37381178, 2024). "An amyotrophic lateral sclerosis-associated mutation in VAPB perturbs these subdomains, likely impairing their remodelling capacity and resulting in impaired interorganelle communication." (PMID 38267577, 2024). "Defective remodeling of ERMCSs is seen with mutations in the VAPB gene that cause the neuro-degenerative disorder amyotrophic lateral sclerosis (ALS)." (PMID 39337270, 2024). "A mutant form of VAPB has been linked to amyotrophic lateral sclerosis and the underlying mechanisms resulting from this defect are studied by researchers in this area to uncover its implication in the disease." (PMID 39916983, 2024). "A gene knock-in model of amyotrophic lateral sclerosis Type 8 based on the VapBP56S mutation and VapB gene deletion has been generated in rats." (PMID 38846532, 2024). "VAPB has been linked to several neurological disorders, including amyotrophic lateral sclerosis (ALS), Alzheimer’s disease (AD) and the α-synucleinopathies, Parkinson’s disease (PD) and multiple system atrophy (MSA)." (PMID 35756994, 2022). "Further ASNA1 interacts with and likely modulates the function of vesicle-associated protein B (VAPB) which is mutated in cases of amyotrophic lateral sclerosis." (PMID 36480541, 2022). "An example is VAPB, a protein mediating vesicle trafficking that is implicated in amyotrophic lateral sclerosis and spinal muscular atrophy." (PMID 35217805, 2022). "Disease causative mutations in VAPB, which have been suggested to alter VAPB's ability to mediate ER-organelle contacts, have been identified in patients with amyotrophic lateral sclerosis (ALS) type 8." (PMID 35611050, 2022). "A mutant version of VAPB, P56S-VAPB, which results from a single point mutation, is involved in a familial form of amyotrophic lateral sclerosis (ALS8)." (PMID 34948065, 2021). "A point mutation in the VAPB gene, resulting in an exchange of proline 56 within the MSP domain to serine (P56S-VAPB), has been linked to a familiar, autosomal-dominant form of amyotrophic lateral sclerosis (ALS8)." (PMID 34948065, 2021). "A mutation in the MSP domain of VAPB (P56S) causes a familial form of amyotrophic lateral sclerosis (ALS) and is also known to reduce FFAT motif-dependent interactions with some proteins." (PMID 34359948, 2021). "VAPA and VAPB are vesicle-associated membrane proteins that are associated with axonal transport of mitochondria and in the case of VAPB implicated in the pathology of amyotrophic lateral sclerosis (ALS8)." (PMID 33137126, 2020). "A point mutation (P56S) in the gene-encoding vesicle-associated membrane-protein-associated protein B (VAPB) leads to an autosomal-dominant form of amyotrophic lateral sclerosis (ALS), classified as ALS-8." (PMID 31936602, 2020). "YIPFβ1A/YIF1A was shown to interact with VAPB, a mutant of which (VAPB–P56S) has been linked to motor neuron degeneration in amyotrophic lateral sclerosis type 8 (ALS8)." (PMID 31417902, 2019). "A mutation (P56S) has been reported in the VAPB MSP domain causing an autosomal dominant form of amyotrophic lateral sclerosis (ALS8) that results in VAPB aggregation and neurotoxicity." (PMID 30717447, 2019).
amyotrophic lateral sclerosis (continued). "Here we show that vesicle-associated membrane protein–associated protein B (VAPB), previously associated with a familial form of amyotrophic lateral sclerosis 8, is an essential HCN1 and HCN2 modulator." (PMID 29879376, 2018). "ALS8 is a late-onset familial autosomal dominant form of Amyotrophic Lateral Sclerosis (ALS) caused by a point mutation (P56S) in the VAPB gene (VAMP associated protein isoform B)." (PMID 28912432, 2017). "Mutations in the VAPB MSPd are associated with amyotrophic lateral sclerosis (ALS) and spinal muscular atrophy (SMA), two motor neuron degeneration diseases." (PMID 28634273, 2017). "Mutations in either VAPB or p97 can cause amyotrophic lateral sclerosis, a neurodegenerative disorder that affects upper and lower motor neurons." (PMID 24885147, 2014). "Strikingly, two point mutations P56S and T46I in the VAPB MSP domain have been identified to lead to familial amyotrophic lateral sclerosis with rapid progression or late onset spinal muscular atrophy." (PMID 22720086, 2012). "The P56S mutation in VAPB causes a dominant, familial form of amyotrophic lateral sclerosis (ALS)." (PMID 40764463, 2025). "However, pathogenic variations, such as P56S, P56H, and T46I, in the VAPB MSP domain lead to the familial form of amyotrophic lateral sclerosis (ALS8)." (PMID 40650266, 2025). "Amyotrophic lateral sclerosis Type 8 is a familial disease caused by mis-sense mutations in VAPB." (PMID 38846532, 2024). "Importantly, dysfunction of VAPB, the human ortholog of Vap33, has been implicated in the development of amyotrophic lateral sclerosis type 8 (ALS8) and spinal muscular atrophy (SMA) 66–68." (PMID 39801516, 2024). "Notably, VAPB, which is the human ortholog of Vap33, is linked to neurodegenerative diseases such as amyotrophic lateral sclerosis type 8 (ALS8) and has been the subject of intensive investigation 66–68." (PMID 39801516, 2024). "Mutations in VAPB cause familiar forms of amyotrophic lateral sclerosis." (PMID 37627263, 2023). "In humans, deficiency in VAPB results in amyotrophic lateral sclerosis (ALS)." (PMID 35336913, 2022). "Mutations in human VAPB, cause amyotrophic lateral sclerosis (ALS)." (PMID 35625553, 2022). "Finally, we focus on how a mutation in VAPB leads to the disruption of cellular homeostasis, causing amyotrophic lateral sclerosis type 8 (ALS8)." (PMID 35756994, 2022). "Finally, we focus on the role of VAP in human disease and discuss how mutated VAPB leads to the disruption of cellular homeostasis and causes amyotrophic lateral sclerosis." (PMID 35756994, 2022). "Interestingly, the P56S point mutant of VAPB that causesfamilial amyotrophic lateral sclerosis (ALS) cannot be secreted." (PMID 34036242, 2021). "Point mutation in VAPB has been identified in amyotrophic lateral sclerosis (ALS) patients." (PMID 32648543, 2020). "Interestingly, mutations in the VAPA homolog VAPB (vesicle-associated membrane protein, associated protein B) have been reported as causative mutations in amyotrophic lateral sclerosis and late-onset spinal muscular atrophy." (PMID 31615574, 2019). "Amyotrophic lateral sclerosis (ALS)-linked protein TDP-43 disrupts MAMs by impairing the VAPB–PTPIP51 complex via activation of glycogen synthase kinase-3β (GSK3β)." (PMID 41367495, 2025). "The P56S missense mutation in VAPB has been associated with familial forms of motor neuron diseases such as typical amyotrophic lateral sclerosis (ALS), atypical ALS, and spinal muscular atrophy." (PMID 41536906, 2025). "A missense mutation (P56S) in VAPB was reported to be associated with motorneuron degeneration in affected amyotrophic lateral sclerosis (ALS) patients." (PMID 36611869, 2022). "VAPB P56S mutation is associated with dominantly inherited familial forms of type-8 amyotrophic lateral sclerosis (ALS)." (PMID 33327665, 2020). "VAPB is shown to be mutated in a familial motor neuron disease, amyotrophic lateral sclerosis (ALS) type 820." (PMID 32376919, 2020).
amyotrophic lateral sclerosis (continued). "A P56S substitution in the VAPB MSPd is associated with amyotrophic lateral sclerosis (ALS) and spinal muscular atrophy (SMA)." (PMID 28634272, 2017). "Three additional mutations of VAPB have since been identified in familial Amyotrophic Lateral Sclerosis (ALS) patients, however, in these cases, the segregation of the mutation with the disease was not demonstrated." (PMID 25409455, 2014). "Mutations in VAPB/ALS8 are associated with amyotrophic lateral sclerosis (ALS) and spinal muscular atrophy (SMA), two motor neuron diseases that often include alterations in energy metabolism." (PMID 24039594, 2013). "Strikingly, two point mutations (P56S and T46I) in the VAPB MSP domain have been identified to lead to familial amyotrophic lateral sclerosis (ALS) with rapid progression or late-onset spinal muscular atrophy." (PMID 22815741, 2012). "ISRIB was found to confer neuroprotection in select animal models in vivo and was recently reported to rescue neurodegeneration of amyotrophic lateral sclerosis (ALS) gene VAPB-iPSC-derived motor neurons." (PMID 40344059, 2025). "Although VAPB is known for its involvement in amyotrophic lateral sclerosis, our identification of VAPB in prostate cancer stems purely from bioinformatic predictions and pathway enrichment." (PMID 41462933, 2025). "In humans, VAPB—the ortholog of Vap33—is similarly secreted in the spinal cord, and its dysregulation leads to amyotrophic lateral sclerosis type 8 (ALS8) and spinal muscular atrophy (SMA)." (PMID 39801516, 2024). "The amyotrophic lateral sclerosis (ALS)-derived VAPB P56S mutant also impaired IRS-1 stability by interfering with the ER-tethering of IRS-1." (PMID 37528084, 2023). "The amyotrophic lateral sclerosis-associated VAPB P56S mutation, residing in the MSP domain responsible for binding to PTPIP51, causes VAPB to aggregate and results in a decrease in the mobility of VAPB at MERCS." (PMID 37498742, 2023). "Finally, amyotrophic lateral sclerosis (ALS) is also seen in conjunction with MERC dysfunctions, where impairment of a key MERC tethering proteins, VAPB (vesicle-associated membrane protein-associated protein B), leads to ALS." (PMID 35399520, 2022). "A proline to serine substitution (P56S) in VAPB, which was identified in an autosomal dominant form of amyotrophic lateral sclerosis, was shown to result in a nuclear envelope defect." (PMID 34200728, 2021). "For example, the expression of mutants such as TorsinA and VAPB are related to dystonia and amyotrophic lateral sclerosis, respectively." (PMID 33436890, 2021). "Mutations in VAPB cause rare forms of spinal muscular atrophy (SMA) and amyotrophic lateral sclerosis 8 (ALS8) in patients." (PMID 32626703, 2020). "Amyotrophic lateral sclerosis is caused by mutations in superoxide dismutase 1 (SOD1) enzyme and vamp-associated protein B/C (VAPB)." (PMID 26089911, 2015). "A single missense mutation within the human VAPB gene is associated in a familial form of atypical amyotrophic lateral sclerosis (ALS), triggering a renewed interest in the VAPB protein and its cellular function in human pathologies." (PMID 23049696, 2012). "It has been implicated in neurodegenerative diseases, including amyotrophic lateral sclerosis (ALS) and hereditary spastic paraplegia (HSP), where mutations in VAPB disrupt the regular interaction with PTPIP51, leading to cellular dysfunction and disease pathology." (PMID 41294815, 2025). "Although the present study focused on generating fungal models of VAPB/ALS8 as a subtype of amyotrophic lateral sclerosis, yeast may serve as a rich source of information for the understanding and modeling of other types of ALS." (PMID 37509182, 2023). "Moreover, expression of a mutant VAPB, which is found in patients suffering from amyotrophic lateral sclerosis, resulted in a dilation of the PNS with membrane vesicles accumulating in the PNS pointing to a function in nuclear envelope maintenance." (PMID 34200728, 2021).
amyotrophic lateral sclerosis (continued). "More recently, PTPIP51 has been implicated in the pathogenesis of amyotrophic lateral sclerosis, a progressive motor neuron degenerative disease, and interaction of PTPIP51 with VAPB was interrupted by TDP-43, a protein closely associated with amyotrophic lateral sclerosis." (PMID 28345618, 2017). "In amyotrophic lateral sclerosis (ALS), a neuromuscular neurodegenerative disorder that causes gradual loss of motor neurons, overexpression of TDP-43, one of the thought initiators of disease, dampens the ER to mitochondria apposition via the VAPB-PTPIP51 tethering complex." (PMID 36092728, 2022). "The critical function of VAPB in native pacemaker channel complexes will be relevant for our understanding of cardiac arrhythmias and epilepsies, and provides an unexpected link between these diseases and amyotrophic lateral sclerosis.—Silbernagel, N., Walecki, M., Schäfer, M.-K." (PMID 29879376, 2018). "VAPB, an ERMCS tethering protein, is mutated in amyotrophic lateral sclerosis (ALS)." (PMID 39026009, 2024). "Moreover, new insights over VAPB-PTPIP51 interaction and ER-mitochondria associations during amyotrophic lateral sclerosis/frontotemporal degeneration (ALS/FTD) can be possible using these techniques." (PMID 33525374, 2021). "Recently, damage to ER-mitochondria signaling involving disruption of the VAPB-PTPIP51 tethers has been linked to the pathogenic process in Parkinson’s disease, fronto-temporal dementia (FTD) and related amyotrophic lateral sclerosis (ALS)." (PMID 30841933, 2019). "The regulation of VAPB-PTPIP51 in amyotrophic lateral sclerosis and frontotemporal dementia (ALS/FTD) by FUS metabolism defects through GSK3β mediated regulation of complex formation and supports disease development." (PMID 38434478, 2024). "Indeed, alterations in ER-mitochondria signalling and the VAPB-PTPIP51 interaction have been related to age-related neurodegenerative diseases, such as Parkinson’s disease (PD), Alzheimer’s (AD) disease and Amyotrophic Lateral Sclerosis (ALS) and Frontotemporal dementia (FTD)." (PMID 37870566, 2023). "They showed a significant reduction in VAPB protein levels in amyotrophic lateral sclerosis iPSC-derived motor neurons but could not detect any cytoplasmic aggregation." (PMID 26089911, 2015).